CSF1R (colony stimulating factor 1 receptor)
Diseases named in the same sentence as CSF1R in open-access papers (continued):
Sharing a sentence is not in itself a finding about the gene and the disease.
tumor (continued). "BLZ945 is a potent and selective CSF-1R inhibitor which was shown to attenuate tumor growth by depleting TAMs and enriching CD8+ T cells in a murine K14-HPV-16 cervical cancer mouse model." (PMID 34771482, 2021). "The anti-tumor effect of combined IT was markedly enhanced by a blockade of the colony-stimulating factor-1 receptor (CSF-1R), but only against TC-1/A9 tumors." (PMID 34205330, 2021). "The use of enzymatic inhibitors and blocking antibodies of CSF1R represents two novel approaches that addresses tumor-stroma interactions in an attractive way." (PMID 33842370, 2021). "Blocking the CSF-1/CSF-1R axis can not only directly treat tumor cells with CSF1R, as a targeted therapy, but also can promote the polarization of TAM and improve the tumor microenvironment, thereby exerting an anti-tumor effect." (PMID 34729112, 2021). "Multiple monoclonal antibodies (mAbs) targeting CSF1R have been developed to disrupt the immunosuppressive tumor microenvironment and are evaluated in early clinical trials." (PMID 34976826, 2021). "In summary, targeting the CSF-1R axis cooperates with rituximab in terms of inhibition of tumor growth, B-cell depletion, and M2 macrophage infiltration." (PMID 33731849, 2021). "Now a day, inhibition of CSF-1/CSF-1R interaction by therapeutic antibody to deplete TAMs and their pro-tumor functions is becoming a prevalent strategy in cancer therapy." (PMID 33805444, 2021). "Inhibition of the CSF-1 receptor (CSF-1R) to target TAMs has been shown to regress tumor formation and increase survival in GBM mouse models." (PMID 33668200, 2021). "Experimental evidence suggests that CSF-1/CSF-1R signaling attracts immune cells called macrophages into the tumor microenvironment which promote the capacity of cancer cells to spread." (PMID 34830923, 2021). "For other tumor types, various combinations with CSF1R-mediated TAM depletion are currently under clinical investigation." (PMID 33842370, 2021). "In contrast, enhanced tumor growth inhibition was observed when anti-CSF1R treatment was initiated early after tumor implantation, which was accompanied by an increase in TME inflammation." (PMID 33511454, 2021). "Even though macrophage reprogramming using CSF1R inhibitors or CSF1 antibodies has been achieved for anti-tumor therapy, their effectiveness is still uncertain in most cancers." (PMID 34248982, 2021). "OLFML2B was highly co-expressed with tumor-associated macrophage markers such as CD14, CD163, CSF1R, ITGAM, and MRC1." (PMID 34868901, 2021). "M2-like tumor-promoting macrophages are the major contributors of CSF1R signaling in the tumor microenvironment, as indicated by the significant correlation of the CSF1R gene with CD163 (M2 human macrophage marker)." (PMID 34067348, 2021). "Immunohistochemical analysis of PDM model 2 using CSF1R, CD68, CD204, and CD163 revealed the presence of tumor-associated macrophage markers." (PMID 34063518, 2021). "Combined IT with ODN1826 and anti-CSF-1R induced the highest anti-tumor effect when a tumor developed in only one of five mice in 60 days." (PMID 34205330, 2021). "In an orthotopic model of PDAC, macrophage depletion via CSF1R inhibition decreased the number of tumor-initiating cells, improved the efficacy of chemotherapy, inhibited metastasis, and unleashed T-cell cytotoxicity." (PMID 34201127, 2021). "Inhibition of CSF1R signaling has been shown to suppress macrophage infiltration and to reduce tumor growth." (PMID 34683963, 2021). "We treated MC38 tumor-bearing mice with rec9F8 or an anti-CSF1-R blocking antibody and found that both decreased MC38 tumor growth, as previously reported." (PMID 34572851, 2021). "Treatment with CSF1R inhibitor resulted in a compensatory upregulation of PD-1/PDL1 pathway in tumor tissue, and its combination with anti-PDL1 was more effective than monotherapies in preventing mesothelioma growth." (PMID 34067348, 2021).
tumor (continued). "Altogether, albeit these observations do not permit definite conclusions, they strongly suggest that the abundance of CSF1R-expressing macrophages abolishes the beneficial effects of tumor-infiltrating CD8 T cells in mesothelioma patients’ survival." (PMID 34067348, 2021). "CSF1R single antibody activity on the tumor microenvironment in this tumor model was also reported earlier." (PMID 34976826, 2021). "As the presence of CSF1R+ macrophages correlates with poor survival in various tumor types, a variety of small molecules and monoclonal antibodies (mAbs) directed at CSF1R are in clinical development, which represents an attractive strategy in tumor therapy." (PMID 34926275, 2021). "We treated this PDM model 2 without the addition of autologous TILs to investigate the effects of anti-CSF1R and anti-PD1 antibodies on the compartment of tumor-associated macrophages infiltrated into respective PDMs." (PMID 34063518, 2021). "CSF1R inhibition conferred a significantly reduced tumor cell proliferation and increased tumor cell apoptosis rates." (PMID 34067348, 2021). "Another potential pathway, currently in early clinical development, is the inhibition of colony-stimulating factor receptor 1 (CSF-1R), which controls macrophage differentiation and alters the bone–tumor microenvironment (NCT02472275, NCT02265536)." (PMID 34208521, 2021). "Meanwhile, dual blockade of PI3kγ and CSF1R using a nano-micelle encapsulating the PI3Kγ inhibitor BEZ235 and CSF1R-siRNA reduced AAMs, increased the abundance of CAMs, and suppressed tumor infiltration of myeloid-derived suppressor cells in mice." (PMID 34201127, 2021). "Though clinical data on the treatment efficiency of repolarizing agents is limited, it is clear that CD47-SIRPα, CD40/CD40L, and CSF-1/CSF-1R molecular pathways are involved in tumor survival and progression." (PMID 34988021, 2021). "Inhibition of CSF1R reversed this effect and induced accumulation of tumor-promoting polymorpho-nuclear myeloid-derived suppressor cells (PMN-MDSC)." (PMID 33670714, 2021). "We implanted SMA-560 tumor cells into the right striatum of VM/Dk mice (day 0) and started the treatment on day 14 with the anti-CSF1R antibody 2G2, or the anti-PD1 antibody RMP1.14 or the respective control antibodies." (PMID 34063518, 2021). "Its ligands are M-CSF (CSF-1), GM-CSF (CSF-2) and IL-34, and their binding to CSF-1R induces differentiation, recruitment to tumor sites, and the survival of monocytes and macrophages." (PMID 34638388, 2021). "Preclinical studies have shown that the CSF-1/CSF-1R signaling cascade not only decreases the number of infiltrating TAMs but also repolarizes M2-like to M1-like phenotypes within the tumor microenvironment." (PMID 33802565, 2021). "Since the presence of CSF-1R+ TAMs correlates with poor survival in several tumor types, targeting CSF-1R represents an attractive strategy to eliminate or potentially repolarize these cells." (PMID 34638388, 2021). "We discuss first the potential of CSF1R-targeted therapy as an attractive concept with regards to the tumor microenvironment in the bone marrow niche." (PMID 33842370, 2021). "The expression of LAPTM5, CSF1R, SLCO2B1 and C1QC was negatively associated with the tumor purity in the LUSC samples." (PMID 33428598, 2021). "CSF1R expression in tumor tissues reportedly correlates with poor prognosis in breast, prostate, and ovarian cancers." (PMID 34681709, 2021). "Significant reduction of TAM was achieved in different tumour models using CSF-1R inhibitors, partly due to the impaired recruitment and maturation of infiltrating monocytic TAMs precursors." (PMID 34950148, 2021). "[89Zr]Zr-DFO-N-suc-CSF1R-mAb still reached the tumor, and due to the relatively high protein dose, CSF1R-positive macrophages were already eliminated within the 72-h exposure." (PMID 34976826, 2021).
tumor (continued). "For instance, a study showed that PLX3397, an antagonist of CSF-1R, inhibited cell proliferation in gliomas and induced tumor regression via depletion of TAMs." (PMID 34178692, 2021). "As the blockade of CSF-1R has been shown to deplete TAMs, or to repolarize them to an M1 anti-tumor phenotype, we next assessed the effects of anti-CSF-1R on TAMs in tumors with reduced MHC-I expression by flow cytometry." (PMID 34205330, 2021). "In order to obtain insights on the clinical impact of the CSF1R/CSF1 axis in mesothelioma, we investigated potential links between tumor CSF1R expression, tumor macrophages and clinical outcomes using the TCGA RNAseq data of mesothelioma patients." (PMID 34067348, 2021). "Several small molecules have been developed against CSF1R, with observed tumor regression and extended survival upon treatment in several murine models of GBM." (PMID 34868044, 2021). "Monoclonal antibody (RG7155) that blocks the CSF-1 receptor (CSF1R) dimerization depleted TAMs from the tumor tissue with an increase of the CD8+/CD4+T cell ratio in an animal model." (PMID 33670714, 2021). "CSF-1R is exclusively expressed by cells of the monocytic lineage and, therefore, the CSF-1/CSF-1R axis has been extensively investigated in tumor models and is paradigmatic of the TAM-cancer cell interaction." (PMID 33731849, 2021). "On the other hand, both wild type (control) treated with SB225002 and knockout mice showed significantly decreased tumor growth at week 3, indicating the involvement of CSF1R+ cells in the TME." (PMID 33544755, 2021). "GBM tumor bearing mice treated with the combination of anti-CSF-1R with focal RT experienced increase in survival, thus indicating that CSF-1R targeting is a promising strategy for irradiated GBM." (PMID 34094969, 2021). "In contrast, anti-CSF1R treatment concurrent with tumor implantation resulted in more robust tumor growth inhibition and evidence of enhanced anti-tumor immunity." (PMID 33511454, 2021). "Surufatinib inhibits VEGFR1, VEGFR2, VEGFR3, FGFR1, and CSF1R (colony stimulating factor 1 receptor) and as such, disrupts tumor angiogenesis and promotes immune invasion." (PMID 34680266, 2021). "Currently, inhibition of CSF-1/CSF-1R interaction by therapeutic antibody to deplete TAMs and their pro-tumor functions is becoming a prevalent strategy in cancer therapy." (PMID 33805444, 2021). "In a phase Ib study with advanced solid tumors, the combination of pexidartinib, a CSF-1R inhibitor, and paclitaxel was well-tolerated, and the combination showed reduced macrophage infiltration in the tumor microenvironment." (PMID 33968034, 2021). "Here, we summarized the biological functions of CSF-1/CSF-1R and reviewed cancer promoting mechanisms regulated by CSF-1/CSF-1R axis in neoplasms, particularly in gastrointestinal tract malignant tumors." (PMID 34729112, 2021). "In summary, the anti-tumor effect was most profound in mice with TC-1/A9 tumors that were treated with combined IT supplemented with anti-CSF-1R." (PMID 34205330, 2021). "In that study, the combination of CSF-1R blockade with anti-PD-1 or anti-CTLA-4 blocking antibody improved anti-tumor immunity in mice refractory to ICB." (PMID 33924237, 2021). "In summary, withholding of CSF-1/CSF-1R interaction would rather augment than suspend the M-CSF-driven pro-tumor activities of M2 macrophages in a long run." (PMID 33805444, 2021). "In a phase‐II study of recurrent glioblastoma, PLX3397 treatment at a daily dose of 1000 mg showed acceptable tolerability and led to both CSF‐1R activity inhibition and TAMs infiltration reduction in tumor tissues." (PMID 33463063, 2021). "To further understand the mechanisms regulating the anti-tumor activity of CSF1R inhibition, we systematically evaluated the impact of an anti-mouse CSF1R blocking antibody on tumor growth and the TME phenotype across multiple syngeneic mouse tumor models." (PMID 33511454, 2021).
tumor (continued). "In some mouse tumor models, blockade of CSF1R has been shown to dramatically reduce TAM density, or promote the induction of pro-inflammatory TAM phenotypes, leading to immune activation and tumor regression." (PMID 33511454, 2021). "In experimental mesotheliomas, combined a highly selective small molecule CSF-1R inhibitor-BLZ945 with an anti-PDL1 agent was more effective in retarding tumor growth compared to each monotherapy." (PMID 34729112, 2021). "In the present study, higher CD40LG expression was observed in tumor tissues with CSF1R c.1085 genotype A_G compared to those with genotype A_A." (PMID 34830445, 2021). "We first assessed the correlation of CSF1R mRNA expression in the tumor microenvironment with the level of immune infiltration using the TIMER2.0 web server." (PMID 34830923, 2021). "Although inhibition of macrophages infiltration in tumor-bearing mice via CSF-1R blockade had a significant effect on tumor regression and survival of CD8+ T cells." (PMID 33805444, 2021). "In solid tumors, cells expressing CSF1R almost exclusively defines a population of tumor infiltrating macrophages." (PMID 33842370, 2021). "We show that CSF1R inhibition impedes mesothelioma progression, abrogates infiltration of TAMs, facilitates an M1 anti-tumor phenotype and activates tumor dendritic and CD8+ T cells." (PMID 34067348, 2021). "CSF1R inhibition impedes mesothelioma progression, abrogates infiltration of TAMs, facilitates an M1 anti-tumor phenotype and activates tumor dendritic and CD8+ T cells." (PMID 34067348, 2021). "Prior work in tumor-bearing mice showed that the depletion of macrophages using anti-CSF1R antibodies abrogates hepatotoxicity observed when gemcitabine is administered 2 days after a CD40 agonist." (PMID 34101617, 2021). "Combinations of IGF-1, NFAT or STAT6 inhibitors with CSF-1R inhibitors partially prevented tumor recurrence." (PMID 34949203, 2021). "Despite substantial macrophage depletion, anti-CSF1R had minimal effects on the anti-tumor immune response in mice bearing established tumors." (PMID 33511454, 2021). "Blocking the CSF-1/CSF-1R signaling pathway interferes with tumor progression by regulating TAM, reducing tumor invasion and proliferation." (PMID 34729112, 2021). "SHH MB subgroup has increased expression of inflammation-related genes (CD14, PTX3, CD4, CD163, CSF1R, and TGFB2) and significantly higher infiltration of tumour-associated fibroblasts than Grp3 MB and Grp4 MB." (PMID 34195095, 2021). "Emactuzumab (RG7155) is a CSF-1R antibody that blocks CSF-1R dimerization in CSF-1R+CD163+ TAMs to deplete them from the tumor microenvironment, alone or in combination with other anti-cancer drugs." (PMID 32326073, 2020). "Using a Csf-1r neutralizing antibody and clodronate liposome treatment to deplete tissue resident macrophages a reduction in tumor size and increased survival of mice was observed." (PMID 32038499, 2020). "CSF-1R blockade induced a profound increase in CAF-mediated MDSC recruitment to the tumor site, thus explaining the mechanism behind CSF-1R therapy limitations." (PMID 32509781, 2020). "M279, a CSF-1R antibody, blocking both CSF-1 and IL-34, has been shown to inhibit tumor growth and improve survival rate in a spontaneous breast tumor model." (PMID 33251232, 2020). "For further verification of the expression of CD4/IFNGR2/CD68/CSF1R as immune signatures in OSA tumor microenvironment, RT-qPCR was performed using mRNA from 45 collected primary surgical tissue samples of OSA primary tumors." (PMID 32850346, 2020). "To assess immune infiltration in different CSF1R expressed groups, we first applied estimate for predicting the presence of infiltrating stromal/immune cells, and tumor purity." (PMID 32850346, 2020). "CSF1R TKI or Ab provide prolonged tumor control and symptom relief for a majority of patients with inoperable or relapsing dTGCT, in first and subsequent lines." (PMID 32433669, 2020).
tumor (continued). "Blocking CSF1R signalling with recombinant antibody-induced apoptosis of cancer cells, depleted TAMs and delayed tumour growth and metastasis." (PMID 31809612, 2020). "CSF-1R has also been a primary target to inhibit MDSC recruitment to the tumour site to constrain tumourgenesis." (PMID 32121014, 2020). "In turn, tumor cell-produced ligands such as colony-stimulating factor 1 (CSF1) signal to CSF1R on TAMs to promote recruitment and M2-like polarization." (PMID 32665556, 2020). "CSF1 participates in the recruitment of TAMs to tumor tissues and the M2 polarization process of TAMs, and the survival, proliferation, and function of TAMs depend to a large extent on the CSF1R signaling." (PMID 33224886, 2020). "The blockade of this CSF-1/CSF-1R interaction presents an attractive approach for preventing the switching of tumor resident macrophages/microglia to the immunoinhibitory M2 phenotype." (PMID 33178210, 2020). "CSF1R blockade by monoclonal antibodies increased therapy response from 33.33% (ICB) to 54.53% (ICB + CSF1R blockade) with only 2 out of 11 mice showing tumor progression of >40% between MRI2 and MRI3 (compared to 6 out of 12 in the ICB cohort)." (PMID 32071302, 2020). "It has recently been reported that CSF-1R inhibitors, such as RG7155 and PLX647, block the CSF-1R signaling pathway, leading to ablation of MDSCs or inhibition of their tumor-promoting functions and reprogramming of TAMs." (PMID 32942545, 2020). "Congruent with this, immunohistochemistry examination of soft tissue tumor patient samples showed increased expression of CSF-1 (M-CSF) and colony stimulating factor receptor (CSF1R) in more aggressive, higher histologic grade tumors." (PMID 33381449, 2020). "Several publications reported that sufficient M2-type macrophages that make depletion occur by blocking CSF-1R antibodies are adequate to suppress tumor growth in tumor models." (PMID 32184777, 2020). "CSF-1R is highly expressed by monocytes (precursors of macrophages) and TAMs which support tumor cell proliferation, motility, and drug resistance." (PMID 32760707, 2020). "ROC curve analysis of ANT and tumor methylation data was conducted and revealed that CSF1R methylation had a potential role in differentiating between cancer and normal tissues." (PMID 32724427, 2020). "In preclinical BRAF-mutant melanoma, co-administration of PLX3397 (CSF1R inhibitor) together with PLX4720 (mutant BRAF inhibitor) effectively sensitizes a PD-1-resistant tumor model to anti-PD-1/PD-L1 therapies." (PMID 32849557, 2020). "The increase in circulating CSF-1 promotes the infiltration of MDSCs to tumor sites through the CSF-1/CSF-1R signaling pathway." (PMID 32942545, 2020). "Compared to radiotherapy alone, selective inhibition of CSF-1R is more effective in assisting radiotherapy to inhibit tumor development." (PMID 32942545, 2020). "In fact, the methylation levels of CSF1R in tumor tissues had a more discrete distribution than those in ANTs." (PMID 32724427, 2020). "Cancer cells expressing high levels of M-CSF, recruit TAMs to the tumor site, via their receptor CSF-1R." (PMID 32656079, 2020). "Colony-stimulating factor 1 receptor deposits were detected at the boundary of the tumor, and were also detected at boundaries of the residual tumor after IRFA." (PMID 32760707, 2020). "Using the 13-point method, it was also suggested that CSF1R protein expression in ANTs was significantly higher compared with that in tumor tissues (P=0.0025)." (PMID 32724427, 2020). "Blockade of Csf1/Csf1R, which is expressed by some TAMs, improved mouse survival and reduced tumor weight." (PMID 33584701, 2020).